IFNG (interferon gamma)
Diseases named in the same sentence as IFNG in open-access papers (continued):
Sharing a sentence is not in itself a finding about the gene and the disease.
psoriasis (continued). "A significant reduction in IFNγ concentration was observed with curcumin but not carnosol treatment, while a trend towards reduced IL-17 concentrations was observed in both carnosol and curcumin treated psoriasis PBMC." (PMID 29980703, 2018). "Similarly, we show that also neutrophils isolated from patients with active psoriasis do not express IL-17F, IL-17B, IL-17C, IL-17D, and IL-17E as well as IL-17RC mRNA when activated by R848, IFNγ plus LPS, and IL-17A in vitro." (PMID 29719541, 2018). "However, it was shown that antagonism of IFNγ using a humanised monoclonal antibody does not significantly improve psoriasis." (PMID 26573299, 2016). "This suggests that IFNγ is not critical in sustaining chronic psoriasis lesions." (PMID 26573299, 2016). "However, both wild type and Ifng-/- chimeras developed skin inflammation to the same extent, indicating that hematopoietic cell-derived IFNγ is not a major contributor to the psoriasis-like skin inflammation." (PMID 26701909, 2015). "A well designed study proved that inhibition of PKCα pathway using Sorastaurin can stabilize Treg phenotype as evidenced by maintenance of high Foxp3 and CD25 expression, and lack of IL-17A and IFNγ production and has shown efficacy in clinical trials of psoriasis." (PMID 26652024, 2015). "Interestingly the cytokine profile in the skin of patients with chronic urticaria mimics that found in patients with psoriasis, psoriatic arthritis, and rheumatoid arthritis with increased expression of TNF-alpha and IL-10 and decreased expression of IL-2 and interferon gamma." (PMID 24167521, 2013). "In human, small numbers of T cells producing both IL-17 and IFNγ have been characterized in peripheral blood, in lamina propria of patients with Crohn’s disease as well as in patients with psoriasis, but currently is it not known how such cells are derived from the naïve precursor cells." (PMID 23110343, 2012). "We also characterised their effects in ex-vivo psoriasis PBMC and report that curcumin, but not carnosol, strongly reduces T cell proliferation and cytokine poly-functionality, with reduced expression of psoriatic cytokines IFNγ, IL-17, GM-CSF and IL-22." (PMID 29980703, 2018).
parasitemia (435 papers, 2004 to 2026). "The same was observed in in vivo infection, where TcPEPCK-sKO infection in IFNγ-deficient mice caused uncontrolled parasitemia and severe pathology, highlighting the critical role of PEPCK in host-pathogen interactions." (PMID 41811196, 2026). "N67 infection stimulates an early type I interferon (IFN-I) response (18–24 h pi) that was linked to the suppression of parasitemia on day 7 pi, whereas N67C infection causes extensive inflammation with a high level of interferon-gamma (IFN-γ)." (PMID 39497038, 2024). "Interferon-gamma (IFN-γ) is the major cytokine involved in parasitemia control but has also been linked to CCM." (PMID 35208732, 2022). "Survival analysis using the time to microscopic parasitemia showed that higher frequency of IFNγ+TNF−CD4+ T cells was associated with a higher probability of remaining TBS−." (PMID 35922467, 2022). "TLR9 engagement is involved in trypanosomosis associated IFNγ induction as well as parasitemia control of T. b." (PMID 34762705, 2021). "The control of parasitemia and resistance to African trypanosomes in mice have been linked to early interferon gamma (IFN-γ) production, which is important for activating macrophages to produce nitric oxide that has both trypanostatic and trypanotoxic effects." (PMID 25875604, 2015). "We first measured whether systemic loss of IFNγ affected parasitemia levels, which could alter the quantity and duration of antigen stimulation." (PMID 40163479, 2025). "Thus, a higher baseline frequency and early decrease of IFNγ+TNF−CD4+ T cells were associated with resistance against parasitemia as detected by thick blood smear positivity." (PMID 35922467, 2022). "IFNγ-deficient mice developed a less severe parasitemia and were able to clear infection." (PMID 34414129, 2021). "The importance of this response for macrophage activation and parasitemia control was confirmed by the fact that C57Bl/6 IFNγ knock-out mice are highly susceptible for trypanosome infections, as already indicated in the section that covered the innate protection against the parasite." (PMID 32218784, 2020). "Parasitemia is inversely associated with elevated levels of IL-1β, IL-1Ra, IL-12, IL-15, IL-17, IFNα, and IFNγ in children co-infected with P. falciparum and G− bacteria, suggesting that the cytokines may induce anti-parasitic activities." (PMID 33193291, 2020). "Furthermore, upregulated IFNγ expression in the spleen and the CNS has been reported to be associated with peripheral parasitic infection in mice." (PMID 26184326, 2015). "Potential background parasitic infection in feral CTRs may, therefore, play an important role in shaping the IFNγ and the associated neutralizing antibody response in flavivirus-challenged feral rabbits." (PMID 26184326, 2015). "We speculate that this is due to the incomplete loss of conversion, with the remaining IFNγ being sufficient to control levels of parasitemia." (PMID 26147567, 2015). "Interestingly the early IFNγ production by γδ+ T cells was significantly increased in IL-22-deficient mice, which might lead to the lower parasitemia in IL-22-deficient mice." (PMID 27311945, 2016). "Evidence indicates that innate immune mechanisms involving macrophages, dendritic cells, and natural killer cells are critical for early control of parasitemia through cytokine production, including interferon-gamma and tumor necrosis factor-alpha." (PMID 42307388, 2026). "Together, these results support a model in which Vγ9Vδ2 T cells are activated through BTN3A1, while IL-12 and TNFα license NK cells to produce IFNγ during parasite infection." (PMID 41452934, 2025). "Although parasitemia on day 6 post-infection was slightly elevated in IFNγ-/- mice (1.2%) compared to WT mice (0.7%), this trend was not significant." (PMID 40163479, 2025). "The levels of IFNγ and nine other cytokines also positively correlated with peak parasitemia and fever." (PMID 38890271, 2024).
parasitemia (continued). "IFNγ-/- mice had a higher peak parasitemia and a modest delay in parasite clearance compared to control mice." (PMID 39452729, 2024). "Ifnγ transcripts were elevated only in the E8.5 and E10.5 infection groups even though all IP mice were experiencing ascending parasitemia at the time that placental analyses were conducted." (PMID 35312688, 2022). "Our data suggest that IL-32γ is contributing to the control of the parasitemia by mechanisms that are dependent on IFN-γ but also by IFNγ-independent pathways." (PMID 35097133, 2022). "E8.5 infected mice had elevated transcripts for Ifnγ, Tnf, Il10, Cox1, Cox2, Sod1, Sod2, Cat, and Nrf2, while Sod3 was the only transcript that correlated with parasitemia." (PMID 35312688, 2022). "To further investigate the functional relevance of CD4+ T cells producing IFNγ+ in resistance against parasitemia, we correlated the frequencies of IFNγ+TNF−CD4+ T with antibody reactivity data to Plasmodium proteins that distinguish TBS+ and TBS- Africans17." (PMID 35922467, 2022). "The acute phase is characterized by high parasitemia and increased production of the pro-inflammatory cytokine interferon-gamma (IFN-γ)." (PMID 36140315, 2022). "Stable Tbet+GATA3+ double positive CD4 T-cell populations were observed during parasitic infections and had decreased IFNγ production upon restimulation." (PMID 35186781, 2021). "Stable Tbet+GATA3+ double positive CD4 T-cell populations are produced during parasitic infections and have low IFNγ production upon restimulation." (PMID 35186781, 2021). "Macrophages and neutrophils produce IL-12, causing natural killer cells (NK cells) to secrete interferon-gamma (IFN-γ), which, in turn, increases the production of IL-12, TNF and nitric oxide, cooperating for the control of parasitemia." (PMID 34869068, 2021). "Interleukin 18 is a pro-inflammatory cytokine and is key to promoting the production of interferon-gamma by NK cells against viral, fungal, bacterial and parasitic infections." (PMID 33013844, 2020). "Together, these data support that CCL3 is important for macrophage control of parasite infection and formation of an IFNγ-triggered TNF- and NO-enriched inflammatory milieu." (PMID 32194558, 2020). "Of note, however, another group using a more virulent strain of Py, Py NL, documented a key role for CD8+ T cells in the control of blood parasitemia, invoking both IFNγ- and Fas-L-dependent protection mediated by the CD8+ T cells and macrophages." (PMID 33519801, 2020). "Both IFN-I responsive and unresponsive Th2 cells can up-regulate IFNγ and increase serum IFNγ levels, providing protection against high parasitemia similarly observed in either IFNAR−/− or IFNAR+/+ mice." (PMID 33193291, 2020). "In vivo antibody based killing of trypanosomes also required the presence of IFNγ-mediated NO production, most likely affecting parasite fitness during peak parasitemia." (PMID 32218784, 2020). "Pyrogenic cytokines such as IL-1β, TNFα, IL-6 and IFNγ were significantly increased in plasma at peak parasitemia when the animals were presenting with clinical illness." (PMID 31536608, 2019). "After anti-ASGM1 treatment and NK cell depletion there was a decrease in IFNγ production and an increase in parasitemia in mice." (PMID 30873151, 2019). "Monocytes primed in vivo by limited IFNγ production were also shown to play a regulatory role in the context of a parasite infection." (PMID 31585982, 2019). "We observed that at the peak of parasitemia, muMT-infected mice presented higher frequency of IFNγ-producing CD4+ T cells than their counterparts in infected WT, but this population rapidly decreased (data not shown)." (PMID 29209313, 2017). "IL-10 expression has also shown to inhibit IFNγ-dependent NO production by macrophages and thereby their ability to control parasitic infections." (PMID 29375545, 2017). "Published data suggests licensed NK cells (activating and inhibitory receptor-expressing cells) produce IFNγ during parasite infection." (PMID 26915066, 2016).
parasitemia (continued). "T. gondii-stimulated NK cell IFNγ drives inflammatory DC differentiation in initial parasite infection to boost DC activation of T cells." (PMID 26915066, 2016). "IFNγ is needed to activate phagocytosis and control parasitemia, while IL10 is crucial for counterbalancing the inflammatory response." (PMID 27802341, 2016). "Here, we show that IL-27 derived from IFNγ responding dendritic cells (DCs) is crucial to drive the differentiation of a specialized Th1-Treg cell subset to limit IFNγ-mediated Th1 inflammation in a parasitic infection setting." (PMID 25658840, 2015). "Despite a 50% reduction in IFNγ-secreting cells following IL-12 and IFNγ blockade, the remaining ~30% of IFNγ+ cells were sufficient to prevent high parasitemia." (PMID 26147567, 2015). "As a consequence of defective negative regulation, mice harboring DCs devoid of IFNγR2 exhibited unrestrained IFNγ responses and suffered exacerbated immune-mediated pathology during parasitic infections." (PMID 25658840, 2015). "Mucosal NK cells play a pivotal role in early protection through their cytolytic function and IFNγ production against bacteria, fungi, viruses, and parasitic infections." (PMID 25197644, 2014). "It is possible that parasite infection down-regulates the IFNγ-induced expression of phosphatases such as suppressor of cytokine signaling 1 (SOCS1), known to negatively regulate STAT1 signaling." (PMID 23527309, 2013). "The parasite infection showed an ELISPOT profile of IFNγ secreting LACK-specific splenocytes somewhat similar to that observed at pre-challenge." (PMID 22715418, 2012). "The parasite infection showed an ELISPOT profile of LACK-specific IFNγ-secreting splenocytes similar to that observed at pre-challenge, or 10 days postchallenge." (PMID 22715418, 2012). "The inducible transcription factor Stat1 transmits the immune-protective effects of IFNγ during viral, bacterial and parasitic infections." (PMID 19381261, 2009). "Another limitation of this study is the use of only two timepoints (0 and 10 dpi), which could have contributed to the absence of detectable expression of key cytokines observed in other models of Apicomplexa parasite infection, such as IFNγ and IL-12." (PMID 41398915, 2025). "IFNγ levels decrease significantly during the participants’ second exposure to high blood stage parasitemia and could contribute to the decrease in symptoms." (PMID 38890271, 2024). "Firstly, during the innate response, T. gondii infection triggers the production of inflammatory cytokines IL-1β, IFNα/β, IL-6, IL-12, IL-15, and IL-18, driving NK cell production of IFNγ, resulting in early control of parasite infection by targeting intracellular parasites." (PMID 37018796, 2023). "Finally, E10.5 infected mice had elevated transcripts for Ifnγ only, with a tendency for Tnf transcripts to correlate with peripheral parasitemia." (PMID 35312688, 2022). "Interestingly, a recent paper showed that IL-18-MyD88 signaling is critical in expanding CD4+IFNγ+ T cells during parasitic infection." (PMID 34093543, 2021). "T cells have also been considered as unresponsive to secrete IFNγ and IL2 cytokines under T. cruzi antigens stimulation in a murine model of infection with parasite and leukemia virus, associated with CDR and higher parasitemia." (PMID 34591866, 2021). "While an early IFNγ-mediated inflammatory response will help to control the onset of parasitemia as well as the height of peak parasitemia, it will also be the source of infection-associated anemia, liver inflammation, and the destruction of the adaptive immune response." (PMID 32218784, 2020). "In addition to IFNγ production, peripheral blood NK cells are thought to be stimulated to be cytotoxic in response to parasite infection." (PMID 30873151, 2019). "Total and IFNγ‐producing NK cells were reduced with parasite infection." (PMID 29113976, 2018).
parasitemia (continued). "The ability of elevated IFNγ levels following virulent challenge with T. evansi to both aid control of parasitemia and simultaneously exacerbate damage to the host may be explained by the varied roles that IFN-γ plays in the host." (PMID 26566996, 2015). "We observed that Il4-expressing Th2 cells could readily produce IFNγ following adoptive transfer in Rag–/–recipients, and these cells reduced severe parasitemia during acute P. chabaudi infection." (PMID 26147567, 2015). "This system permitted us to test whether Th2 cells, which had converted into IFNγ+ cells, could also control high parasitemia following acute infection." (PMID 26147567, 2015). "Thus, type I IFN signaling was dispensable for IFNγ production from ex-Th2 cells and for controlling high parasitemia." (PMID 26147567, 2015). "IFNγ/IL-10 co-producing cells have been described in several parasitic infections and are hypothesized to be important in limiting CD4-mediated pathology, but they may also prevent the development of sterilizing immunity." (PMID 24415936, 2014). "Inappropriate regulation of inflammatory cytokines by HIV-1 infected macrophages in the context of high IFNγ concentrations may prevent an adequate immune response to parasitemia." (PMID 22363802, 2012). "IFNγ is critically involved in the induction of ECM40; thus the prevention of neuropathology by bpV(phen) treatment may have bypassed the IFNγ-mediated pathology of this disease and allowed the increased IFNγ production of the IL-10KO mice to better control their parasitemia." (PMID 28710387, 2017). "There was a trend towards a decrease in temperature and the levels of the top five most upregulated cytokines during the participant’s second exposure to high parasitemia, IL-10, CXCL10, IL-1RA, IFNγ, IL-6." (PMID 38890271, 2024). "We demonstrated that even in the absence of symptomatic infections or asymptomatic urinary or parasitic infections, children with CZS have low CCL2 and CXCL8 production and increased serum levels of IFNγ and IL-13." (PMID 37766239, 2023). "It is known that leishmanicidal mechanisms, such as NO production from macrophages, are activated by IFNγ-producing CD4+ T cells and are further enhanced by TNFα, promoting resistance against parasite infection." (PMID 36851182, 2023). "qPCR data clearly demonstrated that HKLD infection did not have any effect on the regulation of BRG1 expression, thus, suggesting that live parasite infection plays a potential role for the downregulation of the BRG1 expression, even after IFNγ stimulation." (PMID 35433496, 2022). "We assessed the serum levels of six cytokines (i.e. IL-1α, IL-1β, IFNγ, CXCL10, CXCL9, TNFα) at the first peak of parasitemia of both 1/148 and IL3000 infections." (PMID 35787830, 2022). "Homeostatic role of Th1 lymphocytes is to control interactions with pathogens by the formation of interferon gamma (IFN-γ) and IL2, while Th2 lymphocytes by producing IL: 4, 5, 13 play a protective role against parasitic infestation." (PMID 36293300, 2022). "The fact that pro-inflammatory genes of the IFNγ pathway are more strongly elevated at TP4 in Mm than Mf suggests prolonged inflammation only in Mm, despite similar levels of parasitemia in both species at that time point." (PMID 34593836, 2021). "In both species the rise in parasitemia at TP4 is marked by an elevated immune response via IFNα and IFNγ." (PMID 34593836, 2021). "Recognition of this GPI glycosyl core by IFNγ stimulated macrophages results in the induction of TNF, which is the second cytokine that is key to the optimal control of an early peak parasitemia." (PMID 32218784, 2020). "Upregulation of pro-inflammatory cytokines such as IFN-γ (IFNG), IL12, and TNF-α (TNF) during the early stages of infection contributes to protection and resolution of parasite infection." (PMID 33123155, 2020).